FN1 (fibronectin 1)
Diseases named in the same sentence as FN1 in open-access papers (continued):
Sharing a sentence is not in itself a finding about the gene and the disease.
papillary thyroid cancer (21 papers, 2014 to 2025). "FN1 has been proposed as a useful marker for the diagnosis of papillary thyroid carcinoma; however, several studies have observed that the low sensitivity of this staining significantly impairs the utility of FN1 in a diagnostic setting 14,15." (PMID 39744583, 2025). "In this study, we analyzed the TCGA mRNA-seq dataset to assess the expression levels of fibronectin (FN1) and associated integrin subunits, evaluating their relationship with clinical features in papillary thyroid cancer (PTC)." (PMID 40423510, 2025). "The recurrence risk of papillary thyroid carcinoma can be preoperatively predicted using miRNA-221, FN1, and CDKN2A genes." (PMID 39000197, 2024). "FN1 encodes fibronectin that forms insoluble fibrils in connective tissues, and also promotes cell proliferation, migration, invasion, and EMT in papillary thyroid carcinoma." (PMID 38542079, 2024). "FN1 was reported to promote invasive metastasis in papillary thyroid cancer due to its activation by the nf-κb signaling pathway." (PMID 37461041, 2023). "Some studies have suggested that miR-144-3p affects papillary thyroid cancer cell migration and invasion by targeting the FN1 gene, and its relevance was demonstrated by using a double luciferase reporter." (PMID 35692876, 2022). "In conclusion, our study reported that TRIM29 inhibited miR-873-5P biogenesis via lncRNA CYTOR sponging premiR-873 to upregulate FN1 and promoted invasion of papillary thyroid cancer cells." (PMID 32994394, 2020). "It was reported that FN1 is over expression in the Papillary Thyroid Carcinoma and listed as potential biomarker for diagnostics." (PMID 32164602, 2020). "UA inhibits papillary thyroid carcinoma (IHH-4 and TPC-1) cells by classical mechanisms, which inhibits EMT by down-regulating fibronectin-1 (FN1), blocks invasive behaviors of cancer cells, reduces the protein expression of Bcl-2, and activates Caspase-3, which further promotes apoptosis [1065]." (PMID 40490812, 2025).
COVID-19 (20 papers, 2020 to 2025). A disease caused by infection with severe acute respiratory syndrome coronavirus 2. "The upregulated expression of COL10A1/FAP/FN1, the characteristic genes of COVID-19, are potential diagnostic targets for PC, and the upregulated expression of FN1 may promote the progression of PC by activating the PI3K-AKT signaling pathway." (PMID 38063927, 2023). "The proteins COL10A1/FAP/FN1 were found to be common signature genes for COVID-19 and PC, were significantly up-regulated in both diseases and showed good diagnostic efficacy for PC." (PMID 38063927, 2023). "Several altered proteins in the serum of COVID-19 positive asymptomatic donors (FGA, SERPINA1, THBS1) and moreover, in CACs treated with these serum factors (HSPA5, FN1), have been associated with platelet aggregation and coagulation problems." (PMID 35397534, 2022). "While the serum proteomics showed a decrease in the levels of TGFβ1 and an increase in the levels of FN1 in COVID-19 survivors 6 months after discharge." (PMID 35288537, 2022). "TGFβ1 expression was downregulated, whereas FN1 expression was upregulated in COVID-19 survivors 6 months after discharge." (PMID 35288537, 2022). "Consistent with histological evidence of clot formation with increased staining of VWF and fibrin, expression of genes associated with fibrin clot formation (FN1, FGA, and F13A1) was also increased in lung tissue from patients with COVID-19." (PMID 34648357, 2021). "Then, COL10A1/FAP/FN1 were defined as the common signature genes of COVID-19 and PC in this study." (PMID 38063927, 2023). "The clustering typing based on the expression levels of COL10A1/FAP/FN1 of COVID-19 signature genes provides a new typing approach for PC, enabling a more refined analysis of PC and providing a good reference for the sophisticated treatment of PC and further clinical studies." (PMID 38063927, 2023). "The upregulation of the FN1 metabolite in COVID-19 survivors may explain the residual imaging abnormalities observed during the conduction of follow-up of patients with COVID-19." (PMID 35288537, 2022). "Moreover, the plasma proteins HRG, FETUB, KNG1, LCAT, AHSG, and FN1 increase over time in abundance in the Munich cohort, thus suggesting their regulation during COVID-19 disease development." (PMID 34226277, 2021). "In the COVID-19 group, the DEPS with the highest number of edges were MAPK1, MAP2K1, HSP90AB1, and FN1." (PMID 39301288, 2024).
Obesity (19 papers, 2014 to 2025). Accumulation of substantial excess body fat. "In the kidney, despite decreased Hsd11b2, Nox4, and Fn1 expression with obesity, histological analysis revealed extensive glomerular damage, including swelling, increased cellularity, and narrowed Bowman’s space, suggesting significant renal pathology." (PMID 40362895, 2025). "Gene expression analysis of the three ECM structure genes Col1a, Col3a, and Fn1 revealed that only Col1a seemed to be influenced by obesity during its response to the trauma." (PMID 32848828, 2020). "In monocytes, we identified that expression of five genes was significantly upregulated by HFD-induced obesity, including Ccl6, Fn1, Lpl, Pf4 and Retnla." (PMID 32785175, 2020). "In 3T3-L1 adipocytes, we evaluated the effect of organotins on the expression of inflammatory response-related genes such as Lgals9, Fn1, Dcn, Vcam1 and S100a8, which are accordingly related to obesity and insulin resistance." (PMID 28824431, 2017). "Interestingly, ASPC3 was uniquely enriched for COL1A1, COL6A1, FN1, LOX, and LUM, which are fibrosis markers recently associated with a specific subset of PDGFRA+ progenitor cells in murine model of obesity." (PMID 36313560, 2022). "This DS‐induced up‐regulation was aggravated in the presence of obesity, and significant synergy was observed for COL3A1 and FN1." (PMID 31368189, 2019). "Notably, CPN2 (carboxypeptidase N Subunit 2), F5 (coagulation factor V), ECM1 (extracellular matrix protein 1), KNG1 (kininogen 1), FN1 (fibronectin 1), and GPLD1 (glycosylphosphatidylinositol-specific phospholipase D1) were found to be elevated in both human and mouse sEVs under obesity conditions." (PMID 38402239, 2024).
asthma (18 papers, 2010 to 2026). "As such, we investigated how asthma-associated ECM proteins fibronectin (FN1), tenascin-C (TNC) and collagen 4α1 (COL4A1) are altered at a transcriptional and protein level in the absence of RPS4Y1." (PMID 40649992, 2025). "The most significantly differentially expressed gene in asthma cases from CAAPA was FN1 encoding fibronectin." (PMID 38806494, 2024). "In pathways downregulated in asthma cases, hub genes were identified reflecting the importance of impaired wound healing: FN1 and ERBB2 35,36." (PMID 38806494, 2024). "The revealed discrepancy between expressions of collagens I and IV at mRNA and protein levels in mice with asthma is in line with the mRNA/protein ratio of Fn1 observed in asthmatic lungs." (PMID 35625754, 2022). "In the next step, the protein levels of Fn1 and Muc5ac in healthy, asthmatic, and asthma-driven fibrotic lungs were evaluated by IHC staining." (PMID 35625754, 2022). "Here we report the mRNA expression and protein levels of pro-inflammatory and pro-fibrotic markers (IL-6, IFN-β1, CCL2/MCP-1, fibronectin 1 and type I collagen) among BSMCs groups: asthma, COPD, and healthy controls." (PMID 34512638, 2021). "Increased anti-fibrotic effect of 1,25D3 was observed in BSMCs from asthma (FN1 average fold-decrease 6.78 ± 0.65, p < 0.001; COL1A1 average fold-decrease 3.68 ± 1.21, p < 0.05 p = 0.014) compared to BSMCs from COPD." (PMID 34512638, 2021). "Nevertheless, the small set of asthma patients included in this study displayed lower levels of FN1 compared to the sarcoidosis groups and were in line with the healthy controls." (PMID 27259755, 2016). "Finally, HIMF (FIZZ1) is correlated with PTEN inhibition, which leads to the increased expression of type-1 collagen and fibronectin-1 in airway remodeling asthma." (PMID 33800244, 2021). "In addition, we aimed to establish whether polyI:C-stimulation of BSMCs also increased the mRNA expression and protein levels of FN1 and type I collagen, two pro-fibrotic mediators highly expressed in the airways of asthma and COPD patients." (PMID 34512638, 2021). "The 15 most significant DEGs included genes known to play a role in wound healing (FN1, CDH11), immune response (VSIG4, HS3ST4), and asthma drug response (PTHHD4, SPTBN1, FKBP5)." (PMID 38806494, 2024). "The most influential nodes (Fn1, Igf1, Ccl2, C3, Timp1, Cxcl12, Ccl4, Ccr2, Spp1, C3ar1, Cat, Cyp2e1, Muc5ac, Muc5b) were selected for further validation in the OVA-induced asthma and post-asthmatic fibrosis murine model." (PMID 35625754, 2022). "BSMCs treated with polyI:C alone displayed an increase in the mRNA expression of FN1 and COL1A1 compared to untreated cells, and this effect was observed to a higher extent in asthma and COPD as compared to control groups (p < 0.05)." (PMID 34512638, 2021). "Our findings indicated that pro-inflammatory and pro-fibrotic mediators are increased at the baseline in BSMCs from both asthma and COPD, and that TLR3 agonist polyI:C, significantly upregulated IL-6, IFN-β1, CCL2, FN1 and COL1A1 expressions in BSMCs." (PMID 34512638, 2021).
bladder cancer (18 papers, 2007 to 2025). "FN1 encodes fibronectin, a glycoprotein present in a soluble dimeric form in plasma, and itself is a potential urine biomarker for bladder cancer detection." (PMID 33204728, 2020). "In this study, we confirmed the critical role of FN1 in bladder cancer through in-depth analyses, identified it as a potential oncogenic pathway in bladder cancer, and elucidated its functional mechanism in fibroblasts." (PMID 41181151, 2025). "Intercellular communication network analysis revealed a close association between ligands and receptors in different cells, in which cytokines mainly interact through the FN1 (Fibronectin 1) signalling pathway, a finding that highlights the value of FN1 as a potential biomarker for bladder cancer." (PMID 41181151, 2025). "For example, Fibronectin (FN1) is reported to promote melanoma metastasis by inhibiting apoptosis and regulating epithelial-mesenchymal transition (EMT) and is also associated with bladder cancer progression." (PMID 34768768, 2021). "Moreover, FN1, CXCL12, CD3E, LCK, and ZAP70 were key interconnected node genes in PPI networks and are also associated with overall survival in patients with bladder cancer." (PMID 33204728, 2020). "FN1 itself is a potential urine biomarker for bladder cancer detection." (PMID 23383328, 2013). "In addition, the COL1A1 and FN1 genes may affect the progression of bladder cancer by regulating the ECM-receptor interaction." (PMID 38678587, 2024). "To further investigate whether hub genes have an impact on the prognosis of bladder cancer, we performed survival analysis of CXCL8, MDM2, TGFB2, FN1, TIMP1, and RPL22L1, and their impact on tumor stage using TCGA database." (PMID 34276798, 2021). "FN1 has the largest number of interconnected nodes in the PPI, suggesting that it may be involved in multiple aspects of bladder cancer development." (PMID 33204728, 2020).
nasopharyngeal carcinoma (18 papers, 2017 to 2025). A carcinoma arising from the nasopharyngeal epithelium. "FN1 was significantly upregulated in nasopharyngeal carcinoma tissues, leading to the promotion of cancer cell proliferation and invasion." (PMID 39012409, 2024). "It has also been reported that miR-9–3p can inhibit epithelial-mesenchymal transition by down-regulating ITGB1, FN1, and ITGAV in nasopharyngeal carcinoma." (PMID 31164410, 2019). "ZIC2 and OVOL1 may function in nasopharyngeal carcinoma through targeting significantly up-regulated genes (such as PTGS2, FN1, CXCL9 and CXCL10) in the Transcription factor-differentially expressed gene regulatory network (e.g., ZIC2→PTGS2 and OVOL1→CXCL10)." (PMID 27765529, 2017). "PTGS2, FN1, CXCL9, CXCL10, ZIC2 and OVOL1 might play roles in nasopharyngeal carcinoma." (PMID 27765529, 2017).
renal carcinoma (18 papers, 2010 to 2025). A carcinoma arising from the epithelium of the renal parenchyma or the renal pelvis. "FN1 plays a critical role in metastasis and is associated with advanced stages and higher metastatic potential in patients with renal cancer." (PMID 28678795, 2017). "FN1 was linked with the suppression of apoptosis in renal cancer, but this gene may be associated with the suppression of apoptosis in EOC." (PMID 30970615, 2019). "Higher FN1 mRNA expression has been observed in renal tumor tissues, thus demonstrating the potential prognostic value of FN1 in renal cancer patients." (PMID 34688260, 2021). "FN1 was found overexpressed also in renal cancer cells and reported as a determinant for renal cancer aggressiveness." (PMID 30911020, 2019). "Furthermore, Waalkes demonstrated that advanced-stage renal cancer patients exhibited increased FN1 expression when compared with patients exhibiting organ-confined diseases." (PMID 24765172, 2014). "Using the co-expression tool on expression data extracted from renal cancer cell samples of CCLE, we obtained lists of genes that were co-expressed with FN1, C3, and C3AR1 and harbored a correlation coefficient > 0.5 or < − 0.5 and P-value < 0.01." (PMID 34688260, 2021). "Higher expression of FN1 has been reported in various cancers including HNSCC, renal carcinoma and lung cancer." (PMID 33931671, 2021). "The CAFs-containing stroma without DES staining had higher FN1 and FAP staining than did the renal cancer cells." (PMID 33634098, 2020).
coronary artery disease (15 papers, 2016 to 2026). "Notably, APOE and FN1 were associated with coronary artery disease." (PMID 39406990, 2024). "For example, the network includes fibronectin 1 (FN1), which is involved in cell adhesion and migration processes including wound healing, blood coagulation, and host defence; genetic polymorphisms within this gene have been associated with adverse lipid levels and coronary heart disease." (PMID 31102408, 2019). "Variations in FN1 were related to coronary artery disease, myocardial infarction, circulating concentrations of cholesterol, apolipoprotein B, C-peptide, and waist-to-hip ratio with even “very strong” or “compelling” evidence of genetic support." (PMID 39143620, 2024). "However, further experiments are warranted to understand the mechanisms underlying Fn1 inhibition of LKB1-AMPK signaling and test whether Fn1 targeting represents a novel target for intervention of ischemic heart diseases in other animals." (PMID 35602095, 2022). "In conclusion, the current study identified that blocking Fn1 protects against myocardial I/RI likely through activating the LKB1-AMPK-dependent signals and highlights that inhibition of Fn1 may be a novel therapeutic option for treating ischemic heart diseases." (PMID 35602095, 2022). "In human tissues, FN1, GP1BA, and PF4 were all upregulated in Sudden death from coronary heart disease (SD-CHD) myocardial samples, with FN1 showing the greatest increase." (PMID 41828395, 2026).
glaucoma (15 papers, 2019 to 2025). Increased pressure in the eyeball due to obstruction of the outflow of aqueous humor. "Also related to “ECM organization”, were 3 other genes (Fbln1, Fn1, and Loxl1) known to be associated with different types of glaucoma." (PMID 38272861, 2024). "The expression of glaucoma-associated transcripts (CTGF, FN1, PAI1, and SFRP1) was measured via qPCR and assessed using one-way ANOVA followed by Dunnett’s post hoc testing on the log-transformed values." (PMID 40650044, 2025). "The top node degree fibronectin 1 (FN1) was reported to be involved in the pathogenesis of glaucoma." (PMID 33195434, 2020). "As we all known that, FN1 is a discovered gene that participated in the regulatory processes of extracellular matrix in glaucoma." (PMID 31680442, 2020). "After this filter, 26 up‐regulated genes/proteins and 59 down‐regulated genes/proteins were identified, including the famous molecule of glaucoma, such as fibronectin (FN1) and connective tissue growth factor (CTGF)." (PMID 31680442, 2020). "Moreover, in module 2, FN1 is the famous molecule in pathogenesis of glaucoma." (PMID 31680442, 2020). "FN1 and CTGF were both down‐regulated in glaucoma cells (GTM3 cells)." (PMID 31680442, 2020). "Fibronectin 1 (FN1) had the highest closeness and betweenness centrality values in our network and was found to be upregulated in immortalized and primary human TM cells through a stimulation of the αvβ3 integrin pathway and contributes to increased TM resistance in glaucoma." (PMID 39458974, 2024). "Interestingly, we found 8 genes (FN1, THBS1, EPHB2, FGF2, DAB2, CD9, PLAUR and ITGA4) were crucial, suggesting that these genes might function as key factors in the pathogenesis of glaucoma." (PMID 31680442, 2020). "Elevated FN1 levels with reducing MMP-9 activity despite increased TGF levels in severe disease stages suggest an escape of the downstream ECM related pathways and alternate control by non-canonical pathways as glaucoma sets in." (PMID 33914756, 2021).
Hypertension (15 papers, 2015 to 2025). The presence of chronic increased pressure in the systemic arterial system. "In this report, we present two cases of GFND, father and son, with nephrotic syndrome, hematuria and hypertension associated with a novel FN1 mutation." (PMID 31419955, 2019). "For example, FN1 expression in blood has been associated with hypertension where increased expression was seen in hypertensive patients, being involved in protective mechanisms that limit organ damage." (PMID 28103909, 2017). "NAIs attenuate nicotine-induced endothelial dysfunction in hypertension by inhibiting AP1-mediated FN1 and SPP1 activation, providing novel insights for smoking-associated cardiovascular risk." (PMID 40722963, 2025). "The possibility that up-regulation of TGFβ1 gene expression in RPTCs and its downstream targets Fn1 and Col 1α, leading to higher tubulointerstitial fibrosis that facilitates the development of hypertension has received considerable attention." (PMID 31040360, 2019). "Altogether, we found nine genes (Cst3, Cyp11b2, Ephx2, Fn1, Igfbp2, P2rx4, Prkcd, RT1-Ba, and Sult1a1) annotated in the RGD as associated with hypertension in this group." (PMID 26822062, 2016). "Additionally, this study found that fibrotic markers Col1a1, Col3a1, and Fn1, as well as renal interstitial fibrosis, were significantly reduced following macrophage depletion in existing hypertension." (PMID 41175639, 2025). "We also identified 21 DEGs (e.g., Fn1, Cd34, Plpp3, Tns1, Nox4, and Npnt) that may be involved in the development of hypertension." (PMID 34862465, 2021). "The effects of Fn1 and Cd34 on hypertension warrant further study." (PMID 34862465, 2021). "Moreover, we had a number of suggestive genes arise from our vascular tissue data, highlighted as having specific effects on the ECM including TIMP2, PSAP, FN1, VCAN, and LOX, each of which have been previously implicated in hypertension." (PMID 30931314, 2019). "Our findings identify FN1 and SPP1 as pivotal molecular targets linking endothelial dysfunction to hypertension, offering novel therapeutic insights for the prevention and treatment of cardiovascular diseases associated with nicotine exposure." (PMID 40722963, 2025).